TRPV6 (transient receptor potential cation channel subfamily V member 6)
Description:
Calcium selective cation channel that mediates Ca(2+) uptake in various tissues, including the intestine. Important for normal Ca(2+) ion homeostasis in the body, including bone and skin (By similarity). The channel is activated by low internal calcium level, probably including intracellular calcium store depletion, and the current exhibits an inward rectification. Inactivation includes both a rapid Ca(2+)-dependent and a slower Ca(2+)-calmodulin-dependent mechanism; the latter may be regulated by phosphorylation. In vitro, is slowly inhibited by Mg(2+) in a voltage-independent manner. Heteromeric assembly with TRPV5 seems to modify channel properties. TRPV5-TRPV6 heteromultimeric concatemers exhibit voltage-dependent gating.
Synonyms: CaT1; ECaC2; ABP/ZF; CATL; HRPTTN; HSA277909; LP6728; ZFAB
Tractability: Small molecule: a structure with a bound ligand is known; a high-quality ligand is known; it belongs to a druggable protein family. Antibody: UniProt places it where antibodies can reach, with high confidence; its Gene Ontology location is reachable by antibodies, with high confidence; UniProt predicts a signal peptide or a membrane-spanning region. PROTAC: a small molecule that binds it is known.
Target class: Voltage-gated ion channel; Ion channel; Transient receptor potential channel
Gene: Protein-coding gene on chromosome 7 (142,871,208 to 142,885,745, reverse strand). Ensembl gene ENSG00000165125.
Subcellular location: Cell membrane
Pathways (Reactome):
Transport of small molecules: TRP channels
Gene Ontology:
Molecular function: calcium channel activity; calmodulin binding; protein binding; identical protein binding; monoatomic ion channel activity
Biological process: calcium ion import across plasma membrane; calcium ion transmembrane transport; calcium ion transport; calcium ion homeostasis; regulation of calcium ion-dependent exocytosis; response to calcium ion; monoatomic ion transport; transmembrane transport
Cellular component: plasma membrane; calcium channel complex; membrane
Genetic constraint (gnomAD): Loss-of-function variants: 41 observed, 83.4 expected, observed/expected ratio (o/e) 0.49, 90% interval 0.38 to 0.64. The upper end of that interval is the gene's LOEUF score, 0.64, which puts it in group 2 of 6, group 1 being the genes least tolerant of losing a copy. Missense variants: 791 observed, 1,027 expected, observed/expected ratio (o/e) 0.77, 90% interval 0.73 to 0.82. Synonymous variants: 362 observed, 398.37 expected, observed/expected ratio (o/e) 0.91, 90% interval 0.83 to 0.99.
Homologues: Orthologues: chimpanzee TRPV6 (99% identical), macaque TRPV6 (99% identical), dog TRPV6 (90% identical), mouse Trpv6 (89% identical), rat Trpv6 (88% identical), guinea pig TRPV6 (85% identical), rabbit TRPV6 (81% identical), pig TRPV6 (76% identical), tropical clawed frog trpv5 (52% identical), tropical clawed frog cat1 (50% identical), tropical clawed frog trpv6 (44% identical), zebrafish trpv6 (44% identical), and 4 more. Paralogues in human: TRPV5 (71% identical), TRPV1 (27% identical), TRPV4 (27% identical), TRPV2 (24% identical), TRPV3 (24% identical).
Diseases named in the same sentence as TRPV6 in open-access papers:
TRPV6 is named in the same sentence as 114 diseases in open-access papers, as found by Europe PMC text mining. Sharing a sentence is not in itself a finding about the gene and the disease. The quoted sentences say what the papers report.
prostate carcinoma (50 papers, 2004 to 2025). A carcinoma that arises from epithelial cells of the prostate gland. "TRPV6 overexpression in human malignancies is now established in thyroid, colon, breast, ovarian, and prostate carcinomas, being associated with tumor aggressiveness." (PMID 37576552, 2023). "It has been possible to establish the involvement of TRPV6 in SOCE in prostate cancer cells, as well as its physical association with ORAI1 via STIM1 and TRPC1 under the conditions of SOCE." (PMID 29671777, 2018). "High expression of TRPV6 mRNA in prostate cancer is closely associated with the elevated degree of aggressiveness of the cancer, assessed by the Gleeson score (grading of the pathological stage) and extraprostatic extension." (PMID 26818094, 2016). "Increased expression of the TRPV6 calcium channel, which would increase intracellular calcium, is associated with prostate cancer tumor progression." (PMID 25344862, 2014). "We genotyped tissue samples from 142 prostate cancer patients and found a similar distribution of TRPV6 alleles as in healthy Caucasians." (PMID 19857260, 2009). "Thus, TRPV6 activity is associated with the survival response of several prostate cancer cell lines (LNCaP, PC-3, and DU145)." (PMID 38534438, 2024). "A high level of expression of TRPV6 is associated with high Gleason score tumours and high metastatic risk, supporting its potential use to predict the clinical outcome of human prostate cancer." (PMID 32931488, 2020). "Similarly, in the TRPM and TRPV family, TRPM8 and TRPV6 are considered oncogenes and their upregulated expression in prostate cancer may constitute new diagnostic markers for that disease." (PMID 22523714, 2012). "Using a cohort of prostate cancer tissue biopsies from patients with a clinical history of at least 10 years after biopsy, we report that TRPV6 expression directly correlates with CRPC tumor aggressiveness and increased risk of metastasis development." (PMID 40908300, 2025). "Existing research studies have suggested that the TRPV6 channel is regulated by androgens; therefore, bicalutamide, an androgen antagonist, has been widely used in the treatment of advanced prostate cancer." (PMID 39109337, 2024). "Multiple papers have indicated that TRPV6 plays a direct role in regulating the growth of prostate cancer cells (specifically the LNCaP cell line)." (PMID 38534438, 2024). "TRPV6 expression increases strongly in high-grade prostate cancer and promotes prostate cancer cell proliferation through a Ca2+/NFAT-dependent pathway." (PMID 38734935, 2024). "The Orai1 protein of the store-operated calcium channel system is necessary for TRPV6′s enhanced trafficking to the plasma membrane, which plays a role in prostate cancer." (PMID 38534438, 2024). "For instance, the elevated expression of TRPM2 is correlated with breast, lung and prostate cancer cell survival, whereas TRPV6 overexpression has been reported in prostate cancer as well as incriminated in breast cancer metastasis." (PMID 39594815, 2024). "This transient activation of TRPV6 and increase in intracellular calcium led to the apoptosis induction in prostate cancer cells with the subsequent death of all cells, which expressed TRPV6 on the plasma membrane." (PMID 36980711, 2023). "The immunoblotting of the total lysates of the prostate cancer cell lines LNCaP, DU-145, PC-3, and PC-3M cells revealed that using rabbit polyclonal anti-TRPV6 antibody rb79 showed an expected size of the glycosylated form of the protein around 95–100 kDa." (PMID 36980711, 2023). "TRPV6 targeting is likely to be prospective and can be used in new combined therapies to control the progression of castration-resistant prostate cancers." (PMID 37576552, 2023). "Translocation of TRPV6 to the plasma membrane and increased aggressiveness was also observed in LNCaP, indicating a clear role for TRPV6 in prostate cancer." (PMID 38136316, 2023).
prostate carcinoma (continued). "The goal of the present study was to describe the TRPV6-specific phenotype and signaling pathways it is involved in, using castration-resistant prostate cancer cell lines." (PMID 37576552, 2023). "In the prostate cancer cell line LNCaP, TRPV6 inhibition can lead to lower levels of proliferation and increased apoptosis." (PMID 38136316, 2023). "In breast and prostate cancer tissues, TRPV6 knockdown appears to impact both cell migration and cell–cell adhesion negatively." (PMID 38136316, 2023). "This transient activation of TRPV6 and increase in intracellular calcium led to the apoptosis induction of prostate cancer cells." (PMID 36980711, 2023). "In the current work, we have undertaken an effort to create a proof of concept for the targeting of the TRPV6 calcium channel in prostate cancer." (PMID 36980711, 2023). "TRPV6 was shown to increase proliferation, and lead cells to a more aggressive phenotype in prostate cancer cell lines." (PMID 38136316, 2023). "The immunoblotting of the same total lysates revealed with rabbit polyclonal anti-TRPV6 antibody rb80 of prostate cancer cells showed a high molecular band of approximately 160 kDa, which was only detected in LNCaP cells." (PMID 36613866, 2022). "It makes one wonder, is there a connection between the TRPV6 generated osteoblastic lesions in prostate cancer and the TRPV6 negative regulated osteoclast differentiation?" (PMID 36071984, 2022). "Elevated TRPV6 mRNA expression was first found in prostate cancer patients and was then also observed in breast, colon, ovary, and thyroid cancers." (PMID 34413465, 2021). "In contrast, increased expression of TRPV6 in prostate cancer cell lines LNCaP and PC-3 correlates with resistance to cisplatin and thapsigargin, hence TRPV6 inhibition enhances cytotoxic effect of these drugs." (PMID 32575381, 2020). "In particular, transient receptor potential vanilloid subfamily member 6 (TRPV6) in prostate cancer reduces the activation of NFAT and decreases cell accumulation in the S phase of the cell cycle." (PMID 33171939, 2020). "The aberrant cell surface expression of TRPV6 in prostate cancer is increased in prostate cancer cells via SOCE-dependent activation of the Annexin I/S100A11 complex." (PMID 32825277, 2020). "Reducing TRPV6 production with siRNA in breast (T-47D) 93, and prostate cancer cell lines (LNCaP) 96 resulted in decreased cell proliferation and increased apoptosis." (PMID 31897233, 2020). "This locational production of TRPV6 was also reported in a study of other prostate tumours 90 and to a degree in prostate cancer cells." (PMID 31897233, 2020). "All these results suggest TRPM8 and TRPV6 channels as potential markers for prostate cancer progression and prognosis." (PMID 32210800, 2020). "We used MDA-MB-231 breast and PC3 prostate cancer cell lines normally expressing both CaSR and TRPV6 at high levels." (PMID 32931488, 2020). "Similar to TRPC6, TRPV6 channel upregulation in prostate cancer cells is known to represent a mechanism for maintaining a higher proliferation rate, increasing cell survival and apoptosis resistance." (PMID 31627357, 2019). "The data also indicated that TRPV6 was the unique TRP gene significantly overexpressed in CRC cells, resembling the previously reported enhanced levels of TRPV6 in prostate cancer." (PMID 31652951, 2019). "For example, the epithelial TRPV6 has been studied extensively in the context of proliferation and cancer, showing increased metastasis and tissue invasion when prostate cancers are TRPV6-positive." (PMID 30134548, 2018). "The work on TRPV6, to date, can serve as a model of calcium-mediated mechanism elucidation leading to translationally relevant results in the prostate cancer field." (PMID 29671777, 2018). "Another member of the TRPV family, TRPV6, is overexpressed in prostate cancer and the expression level has been correlated with tumor grading, suggestive of a potential oncogenic role of TRPV6 in this tumor entity." (PMID 30248976, 2018).
prostate carcinoma (continued). "Up-regulation of the TRPV6 Ca2+ channel in prostate cancer cells was suggested to promote cell proliferation rate, and to increase survival and apoptosis resistance in prostate cancer cells." (PMID 29299148, 2017). "When compared with normal tissue or cells, the increased expression of TRPV6 at the mRNA and protein levels has been observed in prostate cancer, breast cancer and colon cancer." (PMID 26818094, 2016). "Several studies have demonstrated that TRPV6 is over-expressed and promotes the proliferation and invasion in many cancers, such as prostate cancer, breast and colon cancer." (PMID 26818094, 2016). "Substantial expression of TRPV6 mRNA increases with the degree of aggressiveness of the cancer and the degree of metastasis outside the prostate in patients with prostate cancer." (PMID 26818094, 2016). "One study found that TRPV6 mediates Ca2+ uptake into prostate cancer cell, subsequently activating downstream nuclear factor of activated T cells (NFAT) to promote the proliferation rate, and proliferating cell nuclear antigen (PCNA) expression." (PMID 26818094, 2016). "Compared with normal tissue or cells, the expression of TRPV6 mRNA and expression of the TRPV6 protein is substantially increased in prostate cancer tissue." (PMID 27472308, 2016). "Consistently, down-regulation of TRPV6 in prostate cancer cells resulted in decreased cancer cell growth and higher cell death rate." (PMID 27450545, 2016). "Other TRP subfamilies have also been demonstrated in the cancer development, such as TRPM1 in melanoma, TRPM7 in human retinoblastoma cells and human head and neck carcinoma cells, TRPM8 and TRPV6 in prostate cancer." (PMID 23840757, 2013). "In prostate cancer, TRPV6 mRNA levels are positively correlated to tumor progression and aggressiveness as indicated by Gleason score, pathological stage and extra-prostatic metastases." (PMID 23554944, 2013). "TRPM1, TRPM8, and TRPV6 are considered to be tumor suppressors and oncogenes in localized melanoma and prostate cancer, respectively." (PMID 22523714, 2012). "A number of works has already published TRPV6 induction by 1,25-dihydroxyvitamin D3 in intestine, kidney, semicircular canal, and even prostate cancer cells." (PMID 21347289, 2011). "Furthermore, it has been discovered that TRPV6 increases in breast and prostate cancers in an estrogen-dependent manner." (PMID 38534438, 2024). "In short, prostate cancer cells may be able to sustain a greater rate of proliferation, higher cell survival, and resistance to apoptosis because of the overexpression of the TRPV6 Ca2+ channel." (PMID 38534438, 2024). "In prostate cancer cell lines, silencing Numb decreased TRPV6 expression." (PMID 38534438, 2024). "Thus, mAb82 via inhibition of TRPV6 channels activates intrinsic apoptotic pathway via the release of cytochrome C and therefore induces cell death of the prostate cancer cell line LNCaP." (PMID 38879621, 2024). "Our data suggest that the upregulation of key gene targets under TRPV6 suppression or overexpression indicates that TRPV6 plays a crucial role via calcium signaling in angiogenesis, required for dissemination of prostate cancer cells to both adjacent and distant tissues." (PMID 37576552, 2023). "Moreover, TRPV6 messenger RNA (mRNA) expression levels were upregulated with the malignant degree of prostate cancer and the highest levels of TRPV6 were detected in prostate cancer with lymphatic metastases and in recurrent lesions." (PMID 36071984, 2022). "Furthermore, prostate cancer cells expressing TRPV6 were directly inoculated into the bone marrow cavity of tibias and promoted the generation of osteoblastic lesions suggesting TRPV6 promotes prostate cancer bone metastasis via numerous osteoblastic lesions." (PMID 36071984, 2022).
prostate carcinoma (continued). "In particular, TRPC6 and TRPV6 have recently been reported to play a critical role in the development of many carcinomas including human hepatocellular carcinoma, renal cell carcinoma, prostate cancer, lung cancer, and other types of cancer." (PMID 31627357, 2019). "In prostate cancer the expression of TRPV6 was positively correlated to the Gleason score, tumor grade and extra-prostatic growth to a degree that these authors, in the early 2000s, recognized the potential of TRPV6 in diagnosis and prognosis of prostate cancer, and as a target for therapy." (PMID 28150073, 2017). "It has been found that TRPV6 is upregulated in advanced prostate cancer." (PMID 27472308, 2016). "Additionally, TRPV6 has been demonstrated to play a crucial role in promoting the progression of prostate cancer and breast cancer." (PMID 26818094, 2016). "Although elevated TRPV6 expression has been associated with increased aggressiveness of prostate cancer, a potential link between TRPV6 and skin cancer has not been explored." (PMID 27983625, 2016). "Finally, the link between TRPV6 and calcium homoeostasis is in agreement with previous studies performed in other neoplasms such as breast, prostate cancer cells or insulinoma cells." (PMID 27450545, 2016). "Indeed, in the prostate cancer cell line LNCaP, TRPV6 has been proposed as a major source of passive Ca2+ influx in response to the hyperpolarization associated with KCa3.1 channels activation." (PMID 27183905, 2016). "TRPV6 was found to be negatively regulated by androgen in prostate cancer cell line." (PMID 26818094, 2016). "A previously reported 1,25-dihydroxyvitamin D3 antiproliferative activity in prostate cancer may be compromised by TRPV6 upregulation." (PMID 21347289, 2011). "Besides we have already shown that TRPV6 channel is involved in the control of prostate cancer proliferation and apoptosis resistance." (PMID 21347289, 2011). "Furthermore we extracted total RNA from a pool of ten prostate cancer patients and amplified the full length coding sequence of the TRPV6 cDNA." (PMID 19857260, 2009). "Because TRPV6 transcripts are present in advanced prostatic adenocarcinoma samples we asked if the TRPV6 genotype may influence the progression of prostate cancer." (PMID 19857260, 2009). "TRPV6 knockdown or TRPV6 inhibitor can inhibit the proliferation, migration and invasion of cancer cells by regulating calcium signal activation, which has proved to be effective in the treatment of breast cancer, ovarian cancer, prostate cancer and pancreatic cancer." (PMID 35875160, 2022). "In prostate cancer at least, increased trafficking of TRPV6 to the cell membrane with increased calcium influx increases cell proliferation, metastasis and inhibition of apoptosis, and was suggested as a survival mechanism deployed by three prostate cancer cell lines." (PMID 28150073, 2017). "Thus, TRPV6 is currently suggested as a novel target in prostate cancer therapy." (PMID 27450545, 2016). "The question remains open whether 1,25-dihydroxyvitamin D3 treatment is feasible in cancer stages and metastasis being distinct in high TRPV6 expression, or, otherwise, in the prostate cancer cells biopsies still responsive to 1,25-dihydroxyvitamin D3 treatment by overexpressing TRPV6." (PMID 21347289, 2011). "Gkika and colleagues conducted a study of TRP channels in prostate cancer, suggesting that TRPM8 and TRPV6 were novel markers for tumor progression." (PMID 37986367, 2023). "Compared to normal prostate cells, the hormone-responsive and hormone-resistant prostate cancer cells overexpress CACNA1-D, TRPM-7, and TRPV-6." (PMID 38131032, 2023). "Compared to nontumorigenic cells, the hormone-dependent cells overexpressed TRPM-7 and TRPV-6 and the hormone-resistant cells overexpressed CACNA1-D, TRPM-7, and TRPV-6, supporting the role of calcium channels in prostate cancer." (PMID 38131032, 2023).